FOXC2 (forkhead box C2)
Description:
Transcriptional activator.
Synonyms: FKHL14; MFH1; MFH-1; LD
Tractability: PROTAC: UniProt records ubiquitination sites on it.
Target class: Transcription factor
Gene: Protein-coding gene on chromosome 16 (86,566,829 to 86,569,728, forward strand). Ensembl gene ENSG00000176692.
Subcellular location: Nucleus
Subcellular location (Human Protein Atlas): Nuclear bodies; Nucleoplasm
Pathways (Reactome):
Developmental Biology: Formation of intermediate mesoderm; Formation of the ureteric bud
Gene Ontology:
Molecular function: chromatin DNA binding; DNA-binding transcription activator activity; DNA-binding transcription activator activity, RNA polymerase II-specific; identical protein binding; protein binding; RNA polymerase II cis-regulatory region sequence-specific DNA binding; RNA polymerase II transcription regulatory region sequence-specific DNA binding; sequence-specific DNA binding; sequence-specific double-stranded DNA binding; DNA-binding transcription factor activity, RNA polymerase II-specific; promoter-specific chromatin binding; transcription cis-regulatory region binding; DNA binding; DNA-binding transcription factor activity
Biological process: heart development; insulin receptor signaling pathway; lymphangiogenesis; negative regulation of cold-induced thermogenesis; positive regulation of DNA-templated transcription; positive regulation of transcription by RNA polymerase II; response to hormone; anatomical structure morphogenesis; cell differentiation; mesoderm development; negative regulation of transcription by RNA polymerase II; positive regulation of cell adhesion mediated by integrin; positive regulation of cell migration involved in sprouting angiogenesis; positive regulation of endothelial cell migration; positive regulation of vascular wound healing; regulation of transcription by RNA polymerase II; regulation of DNA-templated transcription; somitogenesis
Cellular component: nuclear body; nucleoplasm; nucleus; chromatin
Genetic constraint (gnomAD): Loss-of-function variants: 8 observed, 7.22 expected, observed/expected ratio (o/e) 1.11, 90% interval 0.64 to 1.81. That is too few expected variants to judge how well the gene tolerates losing a copy. Missense variants: 846 observed, 634.61 expected, observed/expected ratio (o/e) 1.33, 90% interval 1.26 to 1.41. Synonymous variants: 436 observed, 295.52 expected, observed/expected ratio (o/e) 1.48, 90% interval 1.36 to 1.6.
Gene-disease validity (ClinGen):
ClinGen rates the evidence that FOXC2 causes each of these diseases.
lymphedema-distichiasis syndrome (autosomal dominant): Definitive. Lymphedema - distichiasis is a rare syndromic lymphedema disorder characterized by lower-limb lymphedema and varying degrees of abnormal growth of eyelashes from the orifices of the Meibomian glands (distichiasis), with occasional associated manifestations.
Homologues: Orthologues: chimpanzee FOXC2 (99% identical), dog FOXC2 (97% identical), pig FOXC2 (97% identical), macaque FOXC2 (93% identical), rat Foxc2 (90% identical), mouse Foxc2 (90% identical), guinea pig FOXC2 (73% identical), tropical clawed frog foxc2 (63% identical), Drosophila melanogaster croc (36% identical). Paralogues in human: FOXC1 (54% identical), FOXE1 (24% identical), FOXS1 (24% identical), FOXL1 (22% identical), FOXA2 (22% identical), FOXD3 (22% identical), FOXD2 (22% identical), FOXA1 (22% identical), FOXD1 (21% identical), FOXE3 (21% identical), FOXF1 (20% identical), FOXI3 (20% identical), and 29 more.
Diseases named in the same sentence as FOXC2 in open-access papers:
FOXC2 is named in the same sentence as 140 diseases in open-access papers, as found by Europe PMC text mining. Sharing a sentence is not in itself a finding about the gene and the disease. The quoted sentences say what the papers report.
breast carcinoma (69 papers, 2009 to 2025). "High levels of FOXC2 expression are associated with basal-like breast cancer, but are less present in luminal breast cancer subtypes." (PMID 23620774, 2013). "The link between FOXC2 and β-catenin has been previously shown by analysis of osteoblast differentiation, and β-catenin and FOXC2 have been individually linked to stemness trait acquisition in various cancers, including breast cancer." (PMID 40227590, 2025). "The FOXC2 transcription factor has been tied to a wide range of disease states, serving as a promising prognostic biomarker associated with aggressive basal-like human breast cancers (increased cancer invasion and metastasis)." (PMID 39473610, 2024). "FOXC2 overexpression was significantly associated with aggressive basal-like human breast cancers." (PMID 37999477, 2023). "Interestingly, FOXC2 is expressed at high level in the claudin low breast cancer subtype associated with CSC and EMT phenotype." (PMID 27815674, 2016). "Therefore, common functional polymorphisms that result in modest alterations in function or expression of the FOXC2 transcription factor may be associated with the development of secondary LE following breast cancer treatment." (PMID 23613720, 2013). "Our results extend these findings by establishing FOXC2 as a key player in breast cancer stem cell metastasis." (PMID 40781106, 2025). "This study establishes SNAIL and FOXC2 as significantly regulated genes in metastatic breast cancer stem cells with clear biomarker and potential therapeutic targeting applications." (PMID 40781106, 2025). "FOXC2 over expression (median: 19.5, p < 0.001) represents a novel finding with significant clinical implications for breast cancer management." (PMID 40781106, 2025). "We then characterized the co-expression of FOXC2 and β-catenin in breast cancer cell lines with either epithelial or EMT-enriched properties." (PMID 40227590, 2025). "The analysis of TCGA data demonstrates a direct correlation between β-catenin expression and FOXC2 expression, with an exceptionally high correlation in basal breast cancers." (PMID 40227590, 2025). "In patients with breast cancer, FOXC2 expression was negatively correlated with the infiltration of B cells and positively correlated with the infiltration of neutrophils and dendritic cells." (PMID 38608123, 2024). "In the context of cancer, particularly breast cancer, FOXC2 is significant for its involvement in several critical processes that promote tumor progression and metastasis." (PMID 39000413, 2024). "FOXC2-target genes also correlated with endothelial genes across breast cancer patient tumors from the METABRIC cohort, though determining the relative contribution of tumor and stroma to this correlation is not possible." (PMID 37499655, 2023). "Analysis of FOXC2 mRNA levels in a large cohort of breast cancer patient samples (METABRIC12) revealed significantly elevated levels in the aggressive Basal/Claudin-low subtypes compared to the luminal and HER2 subtypes." (PMID 37499655, 2023). "When these MSCs were co-cultured with a breast cancer cell model, there was a coincident reduction in EMT-associated genes (e.g., ZEB1/2, TWIST1, SNAIL, FOXC2, N-Cadherin)." (PMID 36940196, 2023). "Excess expression of Twist, Snail, TGFβ, or FOXC2 in breast cancer results in cells that are more mesenchymal and are characterized by cancer stem cell (CSC) markers, i.e., CD44+ and CD24-low." (PMID 38139368, 2023). "For instance, the downregulation of EMT-inducing transcription factors such as Twist, Snail, and Forkhead Box C2 (FOXC2) makes invasive breast cancer cells more chemosensitive by reducing their expression of ABC transporters." (PMID 37304411, 2022). "Elevated level of FOXC2 was found in mouse mammary carcinoma cells undergoing EMT in presence of TGFβ." (PMID 34708244, 2022).
breast carcinoma (continued). "Overexpression of EMT-TFs like Twist, Snail, Slug, Zinc finger E-box binding homeobox 1 (ZEB1) and Forkhead box C2 (FOXC2) are known to induce drug resistance in breast cancer." (PMID 34502361, 2021). "Some researchers reported that FOXC2 suppressed epithelial–mesenchymal transition and multidrug resistance in basal-like breast cancer." (PMID 34645493, 2021). "FOXC2 has been implicated in triple-negative breast cancer progression and therapy resistance, while FOXL1 is reported to inhibit breast cancer cell proliferation, invasion, and migration." (PMID 31910858, 2020). "Administration of this inhibitor induced MET by reversal of E‐ to N‐cadherin switching in breast cancer cell lines expressing high levels of FOXC2, and reduced CSC properties and metastatic capabilities." (PMID 31464093, 2019). "The EMT programme is linked to the acquisition of CSC properties 48, which can be induced by FOXC2, leading to metastases as demonstrated in breast cancer cell line studies." (PMID 31464093, 2019). "Elevated FOXC2 in basal-like breast cancer cells activate EMT-CSC signaling and reduce drug sensitivity." (PMID 35582717, 2019). "Enrichment of aberrant Hh signaling mechanisms in aggressive, metastatic and chemoresistant breast cancers types lead to low levels of E-cadherin and increased expression of FOXC2, SIP1, Snail, and Twist, vimentin, fibronectin and N-cadherin." (PMID 35582717, 2019). "In conclusion, we demonstrate here that a critical regulator of the EMT, FOXC2, also induces metabolic flexibility in breast cancer." (PMID 31652551, 2019). "FOXC2 seems to act as a mesenchymal inductor at a later stage during EMT, and its expression has been associated with aggressive human breast cancers." (PMID 31464093, 2019). "In basal A TNBC and endocrine resistant ER+ breast cancer, we demonstrate that PKCα is an upstream regulator of FOXC2 expression and activity." (PMID 29216867, 2017). "In basal B cell lines, both PKCα and FOXC2 are required for the maintenance of breast cancer stem cells and their in vivo tumorigenicity." (PMID 29216867, 2017). "We sought to determine if the inverse relationship between FOXC2 and p120-catenin is also true in our breast cancer cell lines." (PMID 29216867, 2017). "Downregulation of E-cadherin is one of the critical markers of EMT in human breast cancers, and FOXC2, Twist, ZEB1, ZEB2, Slug, and Snail are transcription factors that repress E-cadherin transcription." (PMID 28212558, 2017). "Together, these data prompted us to further examine the functional consequence of the PKCα, FOXC2, and p120-catenin relationship in breast cancer at the molecular level." (PMID 29216867, 2017). "FOXC2 specifically suppresses E-cadherin and induces the expression of matrix metalloproteinases in breast cancer to promote metastasis." (PMID 27283491, 2016). "Knockdown of FOXC2 expression in breast cancer cells abrogates their metastatic potential, implicating its role in cancer development." (PMID 25785582, 2015). "FoxC2 expression is significantly correlated with highly aggressive basal-like breast cancers, and FoxC2 overexpression increases the metastatic potential of mouse mammary carcinoma cells to the lung." (PMID 22174714, 2012). "Weinberg and colleagues found that expression of FOXC2 was induced in cells undergoing epithelial-mesenchymal transition (EMT), and FOXC2 was correlated with the highly aggressive basal-like subtype of human breast cancers." (PMID 21829474, 2011). "We next asked whether pHi regulates FOXC2 activity for an FkhP sequence in cells by using a luciferase assay with MDA-MB-436 clonal human breast cancer cells." (PMID 40464693, 2025). "The highly significant overexpression of both genes (p < 0.001) combined with substantial fold-changes (SNAIL: 2.55, FOXC2: 2.70) establishes these molecules as reliable indicators of metastatic disease progression and represents a major advancement in understanding breast cancer stem cell biology." (PMID 40781106, 2025).
breast carcinoma (continued). "This study aimed to explore the molecular pathways connecting the long non-coding RNAs (lncRNAs) HOTAIR, UCA1, and MALAT1 with breast cancer stem cell-related genes FOXC2, SNAIL, and ZEB, focusing on their involvement in transcriptional regulation, proliferation, and survival." (PMID 40781106, 2025). "Moreover, the P38-mediated phosphorylation of Ser367 of FOXC2 serves as a regulatory mechanism of ZEB1 in metastatic breast cancer cells." (PMID 35409206, 2022). "Moreover, transcription factors known to trigger EMT such as TWIST, SNAIL, and FOXC2 increase the expression of ABC transporters in breast cancer." (PMID 35075112, 2022). "In breast cancer, FOXC2 is involved in regulating the EMT process and breast cancer stem cells." (PMID 33505426, 2020). "FOXC2 may have a crucial role in the drug-resistant cancer phenotypes, like that of ovarian cancer, nasopharyngeal carcinoma, breast cancer, and osteosarcoma." (PMID 32508532, 2020). "Similarly, FOXC2 (also known as MGH1 and FKHL14) has been linked to metastasis in breast cancer, colorectal cancer (CRC) and osteosarcoma." (PMID 32372224, 2020). "Increased expression of FOXC2 has been linked to oestrogen receptor negative basal‐like breast carcinoma 12 and survival in various cancer types 21, 22, 23, 24, 25, 26, but survival data for FOXC2 has not yet been presented in prostate cancer." (PMID 31464093, 2019). "Samples (n = 270) were evaluated from the tumors of patients with breast cancer; 186 samples were from stage T1-T2 tumors, 84 samples were from stage T3-T4 tumors, and the proportion of FOXC2-positive tumors in each group was 28.5% (53/186) and 20.2% (17/84), respectively." (PMID 30279969, 2018). "In this study, we investigated the interplay among PKCα, FOXC2, and p120-catenin in breast cancer." (PMID 29216867, 2017). "In breast cancer, Mani and colleagues reported that the overexpression of Twist, Snail or FOXC2 not only made the breast cancer cells with more mesenchymal properties, but also with an increased expression of CD44+/CD24-/low breast CSC markers and an increased mammosphere forming efficiency." (PMID 28245823, 2017). "Our reported findings strongly suggest that inhibition of either PKCα or FOXC2 could potentially reduce metastatic events in these two subtypes of breast cancer." (PMID 29216867, 2017). "Yet, it remains unknown whether FOXC2 can actively repress transcription of p120-catenin in breast cancer." (PMID 29216867, 2017). "FOXC2 was overexpressed in invasive breast cancer cell lines." (PMID 27223064, 2016). "However, an earlier study described FoxC2 as a much weaker repressor of E-cadherin in breast cancer cells." (PMID 26758745, 2016). "The FoxC2 gene has been reported to have a higher expression in the claudin-low sub-type of triple-negative breast cancers compared with the basal sub-type and the luminal or Her2-overexpressing breast cancers." (PMID 26797644, 2016). "FOXC2 is an oncogene in breast cancer, colon cancer, and esophageal cancer." (PMID 24647631, 2014). "FOXC2 plays a central role in promoting invasion and metastasis of breast cancer cells." (PMID 23620774, 2013). "Moreover, CDx2 was the most significant predictive biomarker of poor survival, thus highlighting the clinical significance of FOXC2 as a CDx2 repressor that might be relevant to basal-like breast cancer." (PMID 40764669, 2025). "In addition, FOXC2 expression is closely related to poor prognosis of breast cancer." (PMID 33505426, 2020). "Moreover, recent in vitro assays using shRNA revealed roles for FOXC2 in breast cancer metastasis." (PMID 27283491, 2016). "The study on breast cancer evaluated that the overly expressed EMT-TFs, such as FOXC2, SNAIL, and TWIST, enhanced the promoter activity of ATP-binding cassette (ABC) transporters." (PMID 39941895, 2025).
breast carcinoma (continued). "Consistently, ERK/CDK4/6 drug perturbation in E/M cells suppressed FOXC2/p63, FOXM1, self-renewal, organoid formation and mammary tumour growth via epithelial differentiation." (PMID 40764669, 2025). "Analysis of human breast cancer cell lines from the CCLE, stratified by molecular subtype, revealed significantly elevated expression of these FOXC2-target genes, endothelial genes and proteins in the Basal/Claudin-low subtypes compared to luminal subtypes." (PMID 37499655, 2023). "Knock-down of Foxc2/FOXC2 in murine mammary carcinoma 4T1-TVM cells and human MDA-MB-231 claudin-low breast cancer cells, with two different shRNAs, consistently suppressed network formation." (PMID 37499655, 2023). "At the same time, co-culture of mature adipocytes and breast cancer cells can promote cancer cell growth and mediate EMT by enhancing the expression of MCF7 cell Forkhead Box C2 (FOXC2), twist family bHLH transcription factor 1 (TWIST1), and N- and E-cadherin." (PMID 37666813, 2023). "A wide variety of cancers are including breast carcinomas, hepatocellular carcinomas, lymphomas exhibit elevated expression of FOXC1 and FOXC2." (PMID 35409206, 2022). "For instance, FOXC2 is an EMT regulator and promotes cell migration and invasion through EMT in breast cancer, ovarian cancer, prostate cancer, and lung cancer." (PMID 36304306, 2022). "The 4T1 family of isogenic mammary tumors has been used by several researchers to identify important genes that drive breast cancer metastasis such as TWIST1, FOXC2, and CXCR3 39-41." (PMID 35910801, 2022). "EMT-TFs including Twist, Snail, Slug, and Forkhead Box C2 (FOXC2), regulate chemoresistance by increasing the expression of ATP-binding cassette (ABC) transporters in breast cancer, which is important for chemoresistance." (PMID 34150617, 2021). "In concordance, FOXC2 has been found to be required for EMT and the display of mesenchymal-like properties in breast cancer." (PMID 32372224, 2020). "Taken together, these results indicate that downregulation of PAR1 activates the Hippo pathway and thus inhibits the expression of YAP/TAZ, leading to a decrease of Foxc2 and suppression of EMT in breast cancer cells." (PMID 32647142, 2020). "Together, our study demonstrated that Twist-mediated PAR1 expression contributed to YAP/TAZ and Foxc2 activation via suppressing the Hippo pathway, thereby inducing the EMT in breast cancer cells." (PMID 32647142, 2020). "FOXF2 suppresses EMT in breast cancer and is inversely correlated with the EMT activator FOXC2.50,51 We used qRT-PCR to confirm downregulation of FOXF2 and upregulation of FOXC2." (PMID 31942031, 2020). "Many of the genes regulated have previously been shown to correlate with aggressiveness of breast cancer such as CD24, SOX2, Slug, Twist1, CD-133, N-Cadherin, E-Cadherin, FOXC2, ABCG2, c-Myc, IL8, IL6, and IKKβ (activating NF-κB signaling)." (PMID 29552303, 2018). "Among individual transcripts identified by this analysis were several genes known to be associated with the metastatic process (ALCAM, MALAT1) and EMT (SNAI1, GSC, FOXC2, SIP1) and breast cancer stem cells (CD44)." (PMID 29291741, 2018). "In the current study, we describe a novel signaling axis in endocrine resistant breast cancer and basal A TNBC involving PKCα, FOXC2, and p120-catenin that promotes cancer cell migration and invasion, which are considered integral steps in EMT." (PMID 29216867, 2017). "Collectively, our findings demonstrate a novel role for FOXC2 as a regulator of the G2/M transition and elucidate the reason for the observed sensitivity of CSC-enriched breast cancer cells to PLK1 inhibitor." (PMID 27064522, 2016). "Herein, we identify a novel role for the transcription factor FOXC2, which is mostly expressed in CSCs, in the regulation of cell cycle of CSC-enriched breast cancer cells." (PMID 27064522, 2016).